SLC17A1 (solute carrier family 17 member 1)
Description:
Important for the resorption of phosphate by the kidney. May be involved in actively transporting phosphate into cells via Na(+) cotransport in the renal brush border membrane. Plays a role in urate transport in the kidney.
Synonyms: NPT1; NAPI-1; NPT-1
Tractability: Antibody: UniProt places it where antibodies can reach, with high confidence; its Gene Ontology location is reachable by antibodies, with high confidence; UniProt predicts a signal peptide or a membrane-spanning region.
Target class: Transporter; SLC superfamily of solute carriers; Electrochemical transporter; SLC17 phosphate and organic anion transporter family
Gene: Protein-coding gene on chromosome 6 (25,781,532 to 25,832,052, reverse strand). Ensembl gene ENSG00000124568.
Subcellular location: Apical cell membrane
Subcellular location (Human Protein Atlas): Golgi apparatus
Pathways (Reactome):
Transport of small molecules: Sodium-coupled phosphate cotransporters
Gene Ontology:
Molecular function: protein binding; sodium:phosphate symporter activity; transmembrane transporter activity; phosphate transmembrane transporter activity
Biological process: sodium-dependent phosphate transport; urate metabolic process; urate transport; phosphate ion transmembrane transport; phosphate ion transport; sodium ion transmembrane transport; transmembrane transport
Cellular component: apical plasma membrane; membrane; plasma membrane
Genetic constraint (gnomAD): Loss-of-function variants: 43 observed, 44.98 expected, observed/expected ratio (o/e) 0.96, 90% interval 0.75 to 1.23. The upper end of that interval is the gene's LOEUF score, 1.23, which puts it in group 5 of 6, group 1 being the genes least tolerant of losing a copy. Missense variants: 478 observed, 507.64 expected, observed/expected ratio (o/e) 0.94, 90% interval 0.87 to 1.02. Synonymous variants: 155 observed, 182.09 expected, observed/expected ratio (o/e) 0.85, 90% interval 0.75 to 0.97.
Homologues: Orthologues: chimpanzee SLC17A1 (99% identical), macaque SLC17A1 (84% identical), dog SLC17A1 (70% identical), rabbit SLC17A1 (70% identical), rat AABR07027750.1 (66% identical), mouse Slc17a1 (65% identical), pig SLC17A1 (64% identical), guinea pig SLC17A1 (60% identical), zebrafish si:ch1073-513e17.1 (36% identical), zebrafish slc17a5 (33% identical), Caenorhabditis elegans slc-17.2 (28% identical), Drosophila melanogaster MFS14 (27% identical), and 48 more. Paralogues in human: SLC17A2 (49% identical), SLC17A3 (48% identical), SLC17A4 (48% identical), SLC17A5 (37% identical), SLC17A8 (30% identical), SLC17A6 (30% identical), SLC17A7 (29% identical), SLC17A9 (20% identical), SLC37A4 (18% identical), SLC37A1 (17% identical), SLC37A2 (17% identical), SLC37A3 (14% identical).
Diseases named in the same sentence as SLC17A1 in open-access papers:
SLC17A1 is named in the same sentence as 22 diseases in open-access papers, as found by Europe PMC text mining. Sharing a sentence is not in itself a finding about the gene and the disease. The quoted sentences say what the papers report.
gout (32 papers, 2009 to 2025). A condition characterized by painful swelling of the joints, which is caused by deposition of urate crystals. "Among the other genes significantly associated with gout, seven loci have also been previously identified in GWAS, including those in the genes SLC17A1, GCKR, SLC22A11, ADH1B, MLXIPL, RREB1 and SLC16A9." (PMID 41075270, 2025). "The variant p.I269T in SLC17A1 increased urate transport and reduced the risk of gout, which shows the effect of this transporter on SUA." (PMID 38222853, 2024). "This study examines six rare nonsynonymous variants in the SLC22A11, SLC22A13, and SLC17A1 genes found in a cohort of 150 Czech patients of Caucasian origin with primary hyperuricemia and gout." (PMID 38222853, 2024). "The SLC17A1 gene is one of the loci associated with serum urate level and gout and encodes NPT1, which is a Cl-dependent urate transport interacting with NHE-RF3 encoded by the PDZK1 gene." (PMID 31947599, 2020). "The SLC17A1 locus has the third strongest effect on serum urate and has been associated with gout in candidate gene studies in Japanese, European, and Polynesian sample sets ascertained by clinical assessment, where the OR was consistently approximately 1.5." (PMID 25889045, 2015). "SNP rs1183201 in SLC17A1 was also corroborated to be associated with gout in New Zealand Caucasians and rs1165205 in SLC17A3 (in high linkage disequilibrium (LD) with rs1183201 in HapMap-CEU, r2 = 0.889) was replicated in European whites." (PMID 26290326, 2015). "The other transporter is the renal sodium-dependent phosphate transport protein 1 (SLC17A1) which functions as a urate secretor and an SNP analysis in patients with gout identified a significant association with reduced levels of serum UA." (PMID 25268603, 2014). "Here, we aimed to test the SLC17A1 locus for association with gout, in multiple ancestral groups, using cases defined as a diagnosis of gout by the 1977 American College of Rheumatology (ARA) clinical criteria." (PMID 22541845, 2012). "At rs1183201 (SLC17A1), evidence for association with gout was observed in both the Caucasian (odds ratio (OR) = 0.67, P = 3.0 × 10-6) and Polynesian (OR = 0.74, P = 3.0 × 10-3) groups." (PMID 22541845, 2012). "We confirm the SLC17A1 locus as the third associated with gout at a genome-wide level of significance." (PMID 22541845, 2012). "The haplotype data are consistent with the presence of at least one genetic variant influencing the risk of gout at the SLC17A1 locus." (PMID 22541845, 2012). "Another SNP marker, rs1165205 in SLC17A3, which is in strong LD with rs1183201 in SLC17A1 was previously found to be related to serum UA levels and also representing a risk factor for gout." (PMID 19890391, 2009). "In addition, many other genes, such as ABCG2, SLC22A11, and SLC17A1, also showed strong associations with gout, all surpassing the genome-wide significance threshold after the Bonferroni correction test (P = 0.05/19203 = 2.60 × 10−6)." (PMID 41075270, 2025). "In addition, the intronic variant rs1183201 in SLC17A1 has been described as a variant significantly associated with gout." (PMID 38222853, 2024). "Another study in Japan shows that SLC17A1 rs1165196 variants and the I269T mutation significantly reduce the risk of gout due to renal under-excretion and enhance renal urate secretion in patients with gout." (PMID 39850557, 2024). "Specifically, ASW, CHS, and JPT populations could garner less protection against HU or gout because of the lower frequency of the A allele of the rs1183201 (T > A) in SLC17A1 compared to the European population." (PMID 33810064, 2021). "Moreover, one additional SU associated loci (SLC17A1) was found to be associated with gout significantly." (PMID 28642574, 2017). "We investigated the association of the SLC17A1 locus with gout in New Zealand sample sets." (PMID 22541845, 2012). "This confirms the SLC17A1 locus as the third associated with gout." (PMID 22541845, 2012).
gout (continued). "The variant rs1165196 (p.I269T) in SLC17A1 causes an increase in urate transport via NPT1 and, therefore, significantly reduces the risk of gout linked to renal underexcretion." (PMID 38222853, 2024). "Based on previous studies, it is clear that directly targeting the SLC17A1 transporter to enhance its transport function or protein levels can increase renal urate excretion and improve the condition of gout patients." (PMID 39850557, 2024). "Global genome-wide association studies indicated that SLC17A1 rs1165196 and other variants from SLC17A3 are associated with uric acid concentrations and gout." (PMID 37696853, 2023). "This large window in chromosome 6 (56 SNPs) had a strong, positive significant covariance signal and SLC17A1 and SLC17A3 are urate transporters both linked to gout." (PMID 35876900, 2022). "A meta-analysis of GWASs on serum uric acid and gout in 28,283 Caucasian individuals found genome-wide significance for the SLC17A1 SNP with serum urate levels." (PMID 35813212, 2022). "SLC17A1 rs1165196 significantly enhances UA secretion and reduces the risk of RUE gout; while rs9393672 and rs942379 are significantly correlated with female SUA." (PMID 35922835, 2022). "Recent GWASs of clinically defined gout have revealed associations between gout and urate transporter genes, such as ABCG2/BCRP, URAT1/SLC22A12, GLUT9/SLC2A9, NPT1/SLC17A1, all of which are expressed in the proximal tubular cells of the kidney." (PMID 31975031, 2020). "Genome-wide association studies (GWASs) have explored many genes associated with gout, for instance, ABCG2, PKD2, SLC2A9, KCNQ1, SLC22A12 and SLC17A1 for gout disease among individuals of European descent." (PMID 30899057, 2019). "Of these, 13 variants were common (MAF ≥ 5%) and located in known serum urate GWAS loci, including rs2231142 (Q141K) in ABCG2 (beta: 0.22, p = 2.4 × 10−32; OR for gout: 2.05, p = 1.7 × 10−15), and other variants in SLC2A9, ABCG2, GCKR, SLC17A1, and SLC17A414." (PMID 30315176, 2018). "Six of the genes (A1CF, GCKR, ABCG2, TRIM46, SLC17A1 and HNF4G (novel gout-associated gene)) were still significantly associated with gout in males after multiple correction (all PFDR < 0.05)." (PMID 28252667, 2017). "Three SNPs, rs780094 in GCKR, rs1183201 in SLC17A1 and rs505802 in SLC22A12 were confirmed to be significantly associated with gout and SUA concentrations." (PMID 26290326, 2015). "The role of SLC17A1 has been previously evaluated in gout in a Japanese sample set, with the nonsynonymous variant I269T (rs1165196) having the strongest evidence for association (OR = 0.55, P = 0.004, minor allele (269T) protective)." (PMID 22541845, 2012). "We provide, for the first time, a genome-wide level of evidence supporting a role for genetic variation in the SLC17A1 locus in the etiology of gout." (PMID 22541845, 2012). "As expected, many transporter genes such as URAT1/SLC22A12, GLUT9/SLC2A9, ABCG2/BCRP, NPT1/SLC17A1, and OAT10/SLC22A13 were identified as having an association with gout and SU in addition to several enzyme genes, including the ALDH2 gene, which has a pivotal role in alcohol metabolism." (PMID 38137389, 2023). "In addition, five genes (PKD2, SLC2A9, SLC17A1, SLC17A4 and SLC17A2) were determined to influence the risk of gout (all PFDR < 0.05)." (PMID 29497127, 2018). "Among the fourteen genes, six genes (ABCG2, SLC2A9, TRIM46, SLC17A1, A1CF and SLC17A4) affected both the elevation of the serum urate level and the development of gout from hyperuricemia and were identified as risk factors for gout." (PMID 28252667, 2017). "All the urate transporter-coding genes, ABCG2, SLC2A9, SLC17A1 and SLC17A4, showed association with both the serum urate concentration and progression from hyperuricemia to gout and could affect the risk of gout." (PMID 28252667, 2017).
gout (continued). "We found significant association of uric acid concentrations with three gout-related SNPs (rs780094 in GCKR, corrected p = 3.94E−5; rs1183201 in SLC17A1, corrected p = 0.005; rs505802 in SLC22A12, corrected p = 0.003) and of triglycerides with rs780094 (located in GCKR, corrected p = 2.96E−4)." (PMID 26290326, 2015). "Given the likelihood that gene-diuretic interactions exist, one would be prudent to exclude gout cases taking diuretic medication as a potential confounding factor in order to evaluate the direct effect of genetic variation in the SLC17A1 locus on primary gout." (PMID 22541845, 2012). "Here, we provide strong evidence for a role of the SLC17A1 locus in gout in a Caucasian population (rs1183201, OR = 0.67, P = 3.0 × 10-6) that was replicated in Polynesian samples, with the minor allele of rs1183201 also conferring a similar degree of risk (OR = 0.74, Pmeta-analysis = 3.0 × 10-3)." (PMID 22541845, 2012). "NPT1/SLC17A1 is also a urate exporter that is located in the renal proximal tubules in humans, and its common gain-of-function missense variant, rs1165196 (p.I269T), causes gout with renal underexcretion by increasing urate transport without changing its expression levels." (PMID 38137389, 2023). "In a cohort of 150 Czech patients with primary hyperuricemia and gout, we examined all coding regions and exon–intron boundaries of SLC22A11, SLC22A13, and SLC17A1 using PCR amplification and Sanger sequencing." (PMID 38222853, 2024). "Recent reports also show the significance of transporter genes such as ABCG2, NPT1/SLC17A1, MCT9/SLC16A9, and OAT4/SLC22A11, for the pathogenesis of gout." (PMID 24366390, 2014). "None of the variants of the known gout and hyperuricemia-related genes were co-segregated with the disease phenotype in this family, including ABCG2, SLC2A9, SLC22A11, SLC22A12, SLC17A1, SLC17A3, PDZK1, and INHBB." (PMID 39433541, 2024). "Recently, it was found that SLC17A1 and SLC17A3 SNPs are related to SUA levels, which may be involved in the occurrence of gout." (PMID 35922835, 2022). "In this study, HNF4G, SLC17A1 and GCKR played an important role in serum urate concentrations and gout risk in males but not in females, also suggesting the different contributions of genetic effects between different genders." (PMID 28252667, 2017). "Therefore, we performed a genetic association study of these SUA loci (PDZK1, GCKR, SLC2A9, LRRC16A, SLC17A1, SLC16A9, SLC22A11 and SLC22A12) in gout patients and normal control volunteers of Han Chinese origin." (PMID 26290326, 2015). "Six genes (A1CF, ABCG2, SLC2A9, TRIM46, SLC17A1 and SLC17A4) exhibited effects on the development of gout from hyperuricemia in males (all P < 0.05), but none of them exhibited such effects in females (all P > 0.05)." (PMID 28252667, 2017).
hyperuricemia (17 papers, 2017 to 2025). An abnormally high level of uric acid. "It was also found that single nucleotide polymorphism (SNP) on SLC17A1 gene or a mutation in this gene not only leads to decreased UA excretion but raises the blood levels of UA leading to hyperuricemia." (PMID 29850377, 2018). "For example, previous studies reported that gene polymorphism in Uygur Chinese may be correlated with hyperuricemia such as ApoE E4, IL-8, IL-1RL1, IL-18 and SLC17A1 genes." (PMID 32238146, 2020). "Research has shown that SNPs in the SLC17A1 gene decrease uric acid excretion and elevate blood UA levels, contributing to hyperuricemia." (PMID 41075270, 2025). "Intriguingly, we found homozygous Trp258* mutations in SLC22A12 gene causing RHUC1 while concurrent mutations reported to be associated with hyperuricemia were also discovered including ABCG2 (Gln141Lys) and SLC17A1 (Thr269Ile)." (PMID 32375679, 2020). "The development of hyperuricemia has been shown to be associated with multiple genetic factors and the uric acid transporter protein genes SLC2A9 (encoding GLUT9), SLC22A12 (encoding URAT1), SLC17A1 (encoding NPT1) and ABCG2 were most strongly correlated with changes in serum uric acid levels." (PMID 35909538, 2022).
mineral metabolism disorders (1 paper, 2021). "Two alleles associated with increased ALP, rs3923-T (SLC17A1 missense mutation) and rs764284-G (near CYP24A1), were associated with mineral metabolism disorders and intestinal malabsorption." (PMID 33547301, 2021).
nephrolithiasis (1 paper, 2021). The presence of a calculus in the pelvis of the kidney; this is most often composed of mineral salts and proteins. "Several alleles associated with other traits of interest: rs2836882 near PSMG1 associated with ulcerative colitis, multiple SNPs including rs3923 near SLC17A1 associated with disorders in mineral metabolism, and rs17216707 near CYP24A1 associated with nephrolithiasis." (PMID 33547301, 2021).
Obesity (1 paper, 2025). Accumulation of substantial excess body fat. "Furthermore, obesity led to the up-regulation of sodium transporters (Slc13a1, Slc22a8, Slc17a1, Slc17a3) and the down-regulation of structural proteins (Col4a3, Col4a4) as well as Na/K-ATPase subunits encoded by Atp1a1, Atp1b1, suggesting impaired sodium metabolism and underlying renal injury." (PMID 41133844, 2025).
Renal insufficiency (1 paper, 2021). A reduction in the level of performance of the kidneys in areas of function comprising the concentration of urine, removal of wastes, the maintenance of electrolyte balance, homeostasis of blood pressure, and calcium metabolism. "As the first identified member family SLC17 phosphate transporter family, SLC17A1 is proposed to mediate sodium and inorganic phosphate co-transport and believed to be the voltage-driven organic anions transporter which is highly involved in renal insufficiency." (PMID 34630525, 2021).
kidney disease (3 papers, 2020 to 2024). "Chr23 had the largest number of significant effects that peaked in SLC17A1, which was involved in urate metabolism and transport that could contribute to kidney disease." (PMID 38791589, 2024).
tumor (2 papers, 2020 to 2021). "Decreasing RNA expression levels of NAT8, TINAG, and SLC17A1 were associated with lower tumor grade of KIRC." (PMID 34630525, 2021). "DNA methylation levels of NAT8, TINAG and SLC17A1 was accompanied by an increasing tumor T stage." (PMID 34630525, 2021). "Meanwhile, a higher tumor T stage was accompanied by reductions of RNA expression levels of NAT8, TINAG, and SLC17A1." (PMID 34630525, 2021). "However, the role of SLC17A1 in the tumor microenvironment is still unknown." (PMID 34630525, 2021).
cardiovascular disease (1 paper, 2015). "However, further studies are needed to interpret the effects of SLC17A1 polymorphisms on cardiovascular disease." (PMID 26524967, 2015).
SLC17A1 also shares sentences with these, for which no sentence is quoted: infection (2 papers); cancer (1); cyst (1); disorders of iron metabolism (1); Hepatic steatosis (1); hypophosphatemia (1); hypophosphatemic rickets (1); latent infection (1); nephropathies (1); primary sclerosing cholangitis (1); toxoplasmosis (1); type 1 diabetes (1); ulcerative colitis (1).